SMARCA4 (SWI/SNF related BAF chromatin remodeling complex subunit ATPase 4)
Diseases named in the same sentence as SMARCA4 in open-access papers (continued):
Sharing a sentence is not in itself a finding about the gene and the disease.
tumor (continued). "In the present study, we demonstrated a tumor-environment-based paracrine regulation in which miR-155 suppressed SMARCA4 expression through enhancing tumor initiation." (PMID 31137686, 2019). "In line with tumor mRNA analysis, SMARCA4 IHC-negative NSCLC tumors (n = 11) expressed lower levels of cyclin D1 compared to SMARCA4 IHC-positive NSCLCs (n = 82) although not statistically significant (p = 0.105)." (PMID 30718506, 2019). "For example, SMARCA4-CARM1 is an interaction captured only in the Finnish cohort (the tumour-suppressive gene CARM1, interacts with a gene associated with abnormal LDL-C levels and required for tumour cell growth, SMARCA4)." (PMID 31070705, 2019). "During early stages SMARCA4 acts as a tumor suppressor and inhibits dedifferentiation of ductal cells, whereas, at late stages, it induces EMT and promotes tumorigenesis." (PMID 31769422, 2019). "Hence, SMARCA4 loss may also enhance tumor sensitivity to PARPis." (PMID 31850198, 2019). "The expression of SMARCA4 (also called BRG1) was positive in all carcinomas, at equal amounts within the tumour centre and the invasion front." (PMID 29976164, 2018). "In 130 out of the 161 datasets selected, SMARCA4 was found to be more highly expressed in the tumor samples than in the normal samples." (PMID 29391527, 2018). "Only one type of tumor—kidney renal clear cell carcinomas (KIRC) — showed a higher expression of SMARCA4 in normal samples than in tumor samples." (PMID 29391527, 2018). "Three recent studies showed that this tumor is characterized by a very frequent germline and somatic inactivating mutation of the SWI/SNF chromatin-remodeling gene SMARCA4, present in 69–100% of cases with a protein loss occurring in 82–100% of cases." (PMID 29389895, 2018). "SMARCA4 has been suggested to be a tumor suppressor, but some studies have reported SMARCA4 overexpression in advanced cancers, proposing SMARCA4 to be pro-oncogenic." (PMID 29522538, 2018). "Our results demonstrate that expression of SMARCA4 and SMARCA2 have a high prognostic value and challenge the broadly accepted general role of SMARCA4 as a tumor suppressor." (PMID 29391527, 2018). "Taken together, these data suggest that, at least for several types of cancers, high expression of SMARCA4 confers a selective advantage to tumor cells." (PMID 29391527, 2018). "The genes CHD4 and SMARCA4 demonstrate how the landscape of tumor type – driver gene connections can be exploited to identify novel therapeutic targets, especially for patients without a canonical driver mutation." (PMID 29030609, 2017). "Although the ovarian type of RT (SCCOHT) is almost always caused by mutations in SMARCA4, and extra-ovarian RT by mutations in SMARCB1, it is possible for multiple tumour types within the rhabdoid tumour spectrum to be caused by the same mutation." (PMID 27866340, 2017). "Tumor #7 from the stage 1 group provided an example: the SMARCA2 loss was a truncal event, PBRM1 loss was a branch event, while ARID1A and SMARCA4 losses were branch events that happened even later." (PMID 28445125, 2017). "These mutations almost always lead to loss of their encoded protein (SMARCA4 or SMARCB1) by immunohistochemistry, making this an important diagnostic marker for these tumours." (PMID 27866340, 2017). "BRG1 (SMARCA4) is a documented tumor suppressor and a key subunit of the SWI/SNF chromatin remodeling complex that is silenced in many cancer types." (PMID 27486753, 2016). "In mammalian cells, the SWI/SNF complex exhibits the tumor suppressor activity, and SMARCA4/BRG1 protein is one of its two most essential subunits." (PMID 25886974, 2015). "More families with SMARCA4 mutations have to be described to precisely assess the risk of the SCCHT and other neoplasms, and to establish adequate medical care of the mutations carriers." (PMID 25886974, 2015).
tumor (continued). "Instead, the tumor had a nonsense mutation and loss of protein expression of another member of the SWI/SNF chromatin-remodeling complex, the ATPase subunit SMARCA4 (BRG1) due to a homozygous SMARCA4 mutation [c.2032C > T (p.Q678X)]." (PMID 26109171, 2015). "For instance, tumor sequencing has unveiled some of these functional differences: SMARCA2 inactivation by mutation is infrequent in tumor development; however, SMARCA4 has been found mutated in primary tumors and cancer cell lines." (PMID 25391308, 2014). "Tumor-specific mutations in the following SMARCs are especially common: SMARCB1/SNF5, SMARCA2/BRM, and SMARCA4/BRG1." (PMID 24622842, 2014). "Classifying SMARCA4 alterations into Class 1 and Class 2 may have prognostic implications and could help predict the tumor immune microenvironment status (TMB and PD-L1)." (PMID 42124413, 2026). "As a tumor suppressor, SMARCA4 is frequently altered in approximately 20% of human malignancies." (PMID 41577374, 2026). "Inactivation of the SMARCA4 gene, which encodes BRG1 protein, increases tumor invasiveness and affects sensitivity to conventional platinum-based chemotherapeutic agents but may increase tumor sensitivity to EZH2 inhibitors, CDK4/6 inhibitors." (PMID 40661782, 2025). "SMARCA4-deficient NSCLC was correlated with male sex, older age, smoking history, larger tumor size, and a higher tumor proliferation index (higher Ki-67), among other clinicopathological features, while patients demonstrated worse prognosis compared to SMARCA4-intact cases." (PMID 39888726, 2025). "Future studies using longitudinal tumor sampling and phylogenetic analyses could help clarify the role of SMARCA4 timing in tumorigenesis and treatment responses." (PMID 40867304, 2025). "SMARCA4 encodes a subunit of the SWI/SNF chromatin-remodeling complex, which functions as an epigenetic regulator of gene expression and plays a critical role in tumor suppression." (PMID 40076927, 2025). "Approaches such as miR-423-3p mimics or small molecules that inhibit the ability of GAS5 to sponge miR-423-3p could potentially restore the tumor-suppressive activity of miR-423-3p and reduce SMARCA4 levels, thereby inhibiting HCC growth and progression." (PMID 40451925, 2025). "SMARCA4-(BRG1) immunohistochemistry is particularly critical, revealing a loss of nuclear BRG1 staining in tumor cells while adjacent non-neoplastic stromal cells retain staining (serving as internal controls)." (PMID 40896427, 2025). "In our study, we firstly connected the association of SMARCA4 patients’ prognosis and the TCR diversity in both PBMC and tumor infiltrated T cells via TCR-seq technology, exploring the immune microenvironment of the timepoint before ICB therapy of patients’ and the dynamic changes in PBMC." (PMID 41142791, 2025). "Recent studies have shown that NSCLC patients with SMARCA4 mutations (especially homozygous deletions and truncated mutations, which result in loss of BRG protein) are more likely to develop drug resistance, early tumor relapse, and poor prognosis than SMARCA4 wild-type patients." (PMID 40313929, 2025). "In rare cases, tumor development occurs due to inactivation of the SMARCA4 gene." (PMID 41168858, 2025). "Interestingly, only the loss of SMARCA2 was found concomitant with the presence of tumor lepidic components and epidermal growth factor receptor (EGFR) mutations, whereas the loss of SMARCA4 was mutually exclusive with those findings." (PMID 39888726, 2025). "Next generation sequencing of the tumor at baseline showed microsatellite instability high (loss of MLH1 and PMS2 and TMB 15, ARID1A G801FS*32, KRAS Q6H, PIK3CA N1044K, PTEN R130G, SMARCA4 P109FS*194 and SMARCA4 P316FS*10 mutations)." (PMID 40382524, 2025). "Mutation in the SMARCA4 gene, a critical ATPase subunit of the SWI/SNF chromatin remodeling complex, leads to global epigenetic dysregulation, impaired differentiation, and aggressive tumor biology." (PMID 40978036, 2025).
tumor (continued). "As SMARCA4 inactivation is known to be synthetic lethal with CDK4, PP tumours with SMARCA4 mutations and high CDK4 activity may respond well to CDK4/6 inhibitors." (PMID 40849356, 2025). "Demonstration of this mutation and/or loss of immunohistochemical staining with SMARCA4 (BRG1) antibody may, in the correct morphological context, be crucial in the diagnosis of this highly aggressive neoplasm." (PMID 40739655, 2025). "Leveraging advanced bioinformatics techniques, the identification of 12 crucial genes (ETNK1, BICRA, IL-1R1, KDM3A, ARID2, GSK3β, EZH2, NOTCH1, SMARCA4, FOS, CREB1, CASP3) associated with the tumor-suppressing miR-101-3p network stands out as a notable achievement." (PMID 40074445, 2025). "Our presented case reflects the aggressive prognosis of an AT/RT tumor against the background of all therapy and emphasizes that SMARCA4 mutation-causing cases do not have a favorable prognosis." (PMID 40729139, 2024). "Abnormal expression and variation of ARID1A and SMARCA4 in tumor drug resistance." (PMID 39697230, 2024). "Thus, the BRG1 protein, a product of the SMARCA4 gene, acts as a tumor suppressor along with other SWI/SNF subunits." (PMID 39125664, 2024). "Of the 52 SMARCA4-dNSCLCs, 46 (88.5%) presented a pure solid architecture, four (7.7%) presented with solid architecture and focal glandular formations, and two (3.8%) had few scattered tumor cells." (PMID 38374950, 2024). "SMARCA4-UT shows undifferentiated morphology with epithelioid, round or rhabdoid tumor cells." (PMID 38347129, 2024). "Although low SMARCA4 expression might enhance the response to immunotherapy by improving the anti‐tumor immune microenvironment, further studies with larger samples are needed to confirm these findings." (PMID 39322625, 2024). "Moreover, the typically poor clinical outcomes associated with SMARCA4-DTS and SCCOHT align with the limited response to systemic treatment and the aggressive tumor behavior observed in this case patient." (PMID 39439958, 2024). "SMARCA4 is a gene traditionally considered a tumor suppressor." (PMID 38446332, 2024). "Remarkably, combined SMARCA4/ERBB inhibition showed efficacy in delaying tumor growth, even in PDXs derived from tumors after several lines of treatment, supporting the potential of this combinatorial therapy as a therapeutic strategy for the treatment of SCLC." (PMID 39080761, 2024). "The histological morphology of the rhabdoid‐like undifferentiated tumor of unknown primary led us to suspect a SWI/SNF‐deficient tumor, and subsequent immunostaining led to the diagnosis of a SMARCA4‐deficient undifferentiated tumor." (PMID 38923369, 2024). "As MNAC is an HPV-independent neoplasm, it follows a distinct pathophysiology and has been linked to several genetic mutations, including KRAS/NRAS, ARID1A, ARID1B, SMARCA4, and CTNNB1 mutations, along with chromosomal alterations such as gains of 1q, chromosomes 10 and 12, and loss of 1p." (PMID 39797200, 2024). "However, there are differences in tumor cell characteristics between SMARCA4-deficient NSCLC and SMARCA4-UT." (PMID 38903719, 2024). "This, upon absorption by tumor cells, could lead to the inhibition of tumor suppressor genes SMARCA4 and augment the potential of tumor migration." (PMID 39611045, 2024). "Moreover, SMARCA4-UT expresses a high tumor mutation burden (TMB) and genome instability because of the DNA repair activity of BRG1." (PMID 38542211, 2024). "Thoracic SMARCA4-UT tumors are rare neoplasms, with approximately 100 cases reported globally." (PMID 38265099, 2024). "Matched-pair analysis using tumor tissue and peripheral blood revealed multiple somatic mutations in SMARCA4, but no deleterious germline mutations were present." (PMID 38903333, 2024).
tumor (continued). "Tumors harboring SMARCA4 mutations exhibit increased OXPHOS, and the use of OXPHOS inhibitors, such as IACS-010759, can reduce OXPHOS activity, leading to tumor cell death and decreased tumor progression." (PMID 38903719, 2024). "The role of SMARCA4 in tumorigenesis also involves the tumor microenvironment (TME)." (PMID 38542211, 2024). "The most important feature of SMARCA4 (BRG1)-deficient carcinomas was the complete absence of SMARCA4 in tumor cells in all cases, but INI1 expression was preserved." (PMID 38989233, 2024). "In relation to cancer, SMARCA4 has been thought to act as a tumor suppressor." (PMID 38446332, 2024). "The pathological diagnosis confirmed thoracic SMARCA4‐UT tumor." (PMID 39648153, 2024). "It is possible that SMARCA4 promotes or inhibits tumor cell growth." (PMID 39697230, 2024). "SMARCA4-deficient neoplasms are a heterogeneous group of tumors unified by the absence of SMARCA4 expression, which can occur in various tissues." (PMID 39465834, 2024). "Furthermore, HDACi can recover inositol 1,4,5-trisphosphate receptor type 3 (IP3R3) expression and enhance cisplatin sensitivity in SMARCA4/A2-deficent tumor cells." (PMID 38347129, 2024). "In the NKSCC group, it was found that the mosaic expression of SMARCA4 and the age at tumor presentation (p = 0.029) suggest a significant and intriguing correlation that is more prevalent among tumors that developed between the fourth and fifth decades of life." (PMID 39590317, 2024). "This study of an independent White GC cohort aimed to examine the potential tumor biological significance regarding the expression of SMARCA4 and SMARCE1 along with the expression patterns and correlation with other important genetic characteristics like MSI and EBV status." (PMID 36916408, 2023). "Dual loss of SMARCA4 and SMARCA2 also impacts tumor cell growth in PAX3:FOXO1+ARMS." (PMID 37350942, 2023). "However, we did not detect apparent differences to the other three samples in histological appearance and levels of MYC or SMARCA4 in this tumor." (PMID 37919824, 2023). "Interventional trials could enroll multiple rare tumor types based on mutation status, such as the recently opened trial for SMARCB1/SMARCA4-deficient tumors (NCT05286801)." (PMID 37966258, 2023). "Of note, the direction of tumor progression from an initial KRAS mutation appears to dictate subsequent prognosis: median OS is 12 months vs not reached in KRAS to SMARCA4 and KRAS to EPHA3 groups, respectively." (PMID 37749078, 2023). "One possibility is that SMARCA4 is important for tumour viability in the SHH subgroup of MB." (PMID 37433987, 2023). "The Complex I inhibitor IACS-010759 and the glutaminase inhibitor CB-839 both showed strong anti-tumor activities across cell lines and PDX models with SMARCA4/2-loss, suggesting that these clinical agents can be effective in treating SMARCA4/2-deficicent cancers." (PMID 37210563, 2023). "SMARCA4 is known to similarly play a tumour suppressor role in ATRT." (PMID 37433987, 2023). "SMARCA4‐NSCLC tumor cells with two or even multiple nuclei were observed occasionally." (PMID 38124509, 2023). "In several cases, SMARCA4‐NSCLC tumor cells presented nested pattern." (PMID 38124509, 2023). "For example, we show that GAs in genes such as ARID1A, SMARCA4 and ATR are associated with TMB-high status in a tumour type-specific manner and may thus represent additional biomarkers for immunotherapy in these tumour types." (PMID 37821580, 2023). "Thus, there are some discrepancies regarding the functions of SMARCA4 with respect to tumor initiation and progression in the gut." (PMID 36922568, 2023). "Moreover, injection with SMARCA4-knockout SAS cells into nude mice significantly reduced tumor development." (PMID 36902184, 2023). "We discovered eight tumours (HMF) out of 77 with cancers of unknown primary with SMARCA4-d (biallelic) that could be predicted with relatively high accuracy (PR-AUC-E = 0.44; AUROC = 0.85)." (PMID 36883553, 2023).
tumor (continued). "Here, SMARCA4 acts as the main driving gene and SDUS has a low tumor mutation burden." (PMID 37194064, 2023). "Notably, SMARCA4 mutations appear to be restricted to WNT and Group 3 tumours, and are rarely observed in SHH and Group 4 MB tumours." (PMID 37433987, 2023). "We next performed immunohistochemistry (IHC) for SMARCA4 in DMG tumor samples." (PMID 37094128, 2023). "In addition, the tumor growth rate and the tumor weight with SMARCA4 knocked down were significantly lower than those of the control group." (PMID 36902184, 2023). "Patients with SMARCA4‐dNSCLC had high Ki‐67 indices, more than 50% in 59% of patients and more than 30% in 88% of patients, and large tumors, demonstrating the rapid proliferation of this type of tumor." (PMID 37184108, 2023). "Also, SMARCA4 is a crucial regulator of CD44 expression—the most commonly used marker of CSCs—that facilitates tumor invasion and metastasis." (PMID 36674511, 2023). "A total of 88% of the SMARCA4‐dNSCLC patients had a tumor proliferation index (Ki‐67) ≥30%." (PMID 37184108, 2023). "Also, high expression of SMARCA4 or SMARCA2 is frequently associated with an opposite prognosis in cancer, and their levels correlate inversely with the histologic tumor grade." (PMID 36674511, 2023). "The SWI–SNF complex has become a new class of tumor suppressor genes; therefore, epigenetic therapy may also become a new treatment modus operandi for SMARCA4-UT." (PMID 37115343, 2023). "Inhibition of the growth of rhabdoid tumors with lack of the SMARCB1, through knockdown of the SWI/SNF catalytic subunit SMARCA4, suggests that the survival of such tumor cells may depend on the residual activity of the SWI/SNF complex." (PMID 37175555, 2023). "Routine driver gene mutation screening was negative, and tumor tissue immunohistochemistry analysis showed the absence of the BRG1 protein (encoded by SMARCA4)." (PMID 37214462, 2023). "Therefore, SMARCA2 is an attractive target to inhibit in SMARCA4-mutant cancers, utilising the enhanced reliance of tumour cells on BRM to completely prevent activity of the SWI/SNF chromatin remodeling complex and inhibit cancer cell growth." (PMID 37433987, 2023). "In summary, by analyzing the clinical features, gene mutation information, and factors affecting the prognosis of 105 SMARCA4‐dNSCLC patients, we demonstrated that SMARCA4‐dNSCLC is a type of tumor distinct from SMARCA4‐iNSCLC, with poor prognosis and high invasiveness." (PMID 37184108, 2023). "There is growing evidence that SMARCA4 genes and SWI/SNF complexes play a broad role in tumor inhibition, and SMARCA4-UT may cause many molecular pathways to be affected." (PMID 37115343, 2023). "Because the patient had a thoracic SMARCA4‐deficient undifferentiated tumor that was not expected to respond to chemotherapy, and his general condition was poor (PS2), we discussed the best supportive care or immunotherapy with him." (PMID 36523385, 2022). "Additionally, we performed a differential protein expression analysis comparing the ACC, NEC-like IDH2 and NEC-like SMARCA4/ARID1A tumor classes against each other." (PMID 36443295, 2022). "Additionally, given the efficacy of CDK4/6 inhibitors in certain types of cancers harboring SMARCA4 loss, we highlight that the deletion and nonsense variants in CDKN2A (p16) were found in 30% and 35% of our tumor samples, respectively." (PMID 35884575, 2022). "Moreover, the expression of NOTCH3 and SMARCA4 were increased at tumor progression stages III and IV relative to that in the tumor progression stages I and II." (PMID 35900231, 2022). "Therefore, we further investigated the pathology of this tumor by investigating how ARID1A, which is part of the same BAF complex as SMARCA4, changes in SAMRCA4 deficient tumors and examined the expression of SLC11A, a downstream factor of ARID1A." (PMID 35151345, 2022). "Two tumors had a truncating SMARCA4 variant without missense variants, and one tumor had a partial SMARCA4 deletion." (PMID 35964518, 2022).